RORA (RAR related orphan receptor A)
Diseases named in the same sentence as RORA in open-access papers (continued):
Sharing a sentence is not in itself a finding about the gene and the disease.
asthma (continued). "However, the precise roles of RORα in the pathogenesis of asthma are not yet fully understood." (PMID 37387671, 2023). "Interestingly, RORα was also shown to promote epithelial integrity via attenuation of NF-κB transcriptional activity, suggesting that it may play multiple roles in asthma severity." (PMID 34591794, 2021). "Interestingly, genome-wide association studies of asthma have identified RORα (a critical transcription factor for ILC2 development), as well as TSLP, IL-33 and the IL33-receptor (IL1RL1, ST2) as asthma susceptibility genes, supporting the importance of this pathway for asthma." (PMID 31024538, 2019). "Asthma is a disease with demonstrated heritability in humans, and several genes, including the IKZF3-ZPBP2-GSDMB-ORMDL3 locus, HLA-DQ, IL1RL1, IL33, TSLP, SLC22A5, SMAD3, and RORA have been consistently associated with asthma in genome-wide association studies (GWAS)." (PMID 23984888, 2013). "In addition, RORA participates in the lineage commitment of Th17 cells and is required for the development of nuocytes which are lymphoid-derived innate cells that contribute to the development of asthmatic responses in mouse models of asthma." (PMID 23565190, 2013). "Among genes identified in asthma GWAS, ROBO1, RORA, HLA-DQB1, IL2RB and PDE10A showed most consistent expression patterns and from asthma candidate genes, e.g. NOD1, EDN1, CCL5 and HLA-G were identified." (PMID 21699702, 2011). "Among the GWAS asthma genes, ROBO1, RORA, HLA-DQB1, IL2RB and PDE10A were differentially expressed in the human data." (PMID 21699702, 2011). "Among the asthma genes identified in GWAS, ROBO1, RORA, HLA-DQB1, IL2RB and PDE10A showed most significant evidence of involvement in lung development (all adjusted p < 0.001 for differential expression)." (PMID 21699702, 2011). "RORA is a key transcription factor involved in regulating Th17 and ILC2 cells development and may mediate type 2 inflammation in asthma." (PMID 36366542, 2022). "While there was no general over-representation of asthma genes among differentially expressed genes, some asthma genes were consistently differentially expressed in multiple developing lung transcriptomes, e.g. NOD1, EDN1, CCL5, RORA and HLA-G suggesting key functional roles in lung development." (PMID 21699702, 2011). "However, differential expression of some asthma genes was consistent in both developing human and murine lung, e.g. NOD1, EDN1, CCL5, RORA and HLA-G." (PMID 21699702, 2011). "RORA has been shown to play a role in lung development and childhood asthma and studies in mice have shown BACH2 to repress T-cell cytokine production indicating lower levels of this protein in asthma may contribute to unregulated inflammation." (PMID 35386986, 2021). "Thus, the asthma loci IL33, IL1RL1/IL18R1, RORA, and IL13 previously identified by GWAS belong to the same pathway, and could modify airway inflammation and interleukin responses that are crucial for the development of asthma." (PMID 23565190, 2013). "Importantly, in a small group of shift workers with moderate asthma no clear MCC pattern could be identified, while significant differences in REV ERBα/β and RORα/β were observed compared to patients with conventional working hours." (PMID 40131242, 2025).
Obesity (26 papers, 2010 to 2025). Accumulation of substantial excess body fat. "Among the studied melatonin receptor genes, MTNR1B MTNR1A, and RORA showed strong association with both diabetes and obesity." (PMID 40697662, 2025). "As a result, the liver-specific Rorα-deficient mice develop hepatic steatosis, obesity, and insulin resistance when fed on a high-fat diet." (PMID 37022192, 2023). "To better understand the role of RORα in obesity and IR, we independently generated a macrophage RORα-deficient mouse line." (PMID 33273527, 2020). "Liver-specific Rorα-deficient mice develop hepatic steatosis, obesity and insulin resistance when challenged with a high-fat diet (HFD)." (PMID 28757615, 2017). "Here, we report that RORα plays a key role to control hepatic lipid metabolism to protect against diet-induced obesity and hepatic steatosis, using liver-specific Rorα-deficient mouse model." (PMID 28757615, 2017). "Staggerer (RORAsg/sg) mice with a natural RORA deficiency are protected against age- or diet-induced obesity, hepatosteatosis, and adipose tissue-associated inflammation." (PMID 27556492, 2016). "RORα-deficient mice are protected against age- and diet-induced obesity, hepatosteatosis, and insulin resistance." (PMID 23355833, 2013). "In addition, there is evidence that in the context of adipose tissue inflammation, as associated with obesity, RORα is capable of driving inflammation." (PMID 33767712, 2021). "Moreover, some studies observed a link between circadian gene REV-ERBα, REV-ERBβ, and RORα polymorphisms and obesity and diabetes." (PMID 35053018, 2021). "The RORα‐deficient staggerer (sg/sg) mouse is lean and resistant to diet‐induced obesity." (PMID 29673115, 2018). "A rearrangement resulting in disruption of human RORα1 was found to be associated with severe obesity, while a recent GWAS study showed an association between a single nucleotide polymorphism in RORα (rs7164773) and increased risk for type 2 diabetes in the Mexico Mestizo population." (PMID 23355833, 2013). "Furthermore, the gene RORA has been implicated in severe obesity in humans and mice." (PMID 36806387, 2023). "Specifically, RORA is required for the development of type II innate lymphoid cells and mice lacking the gene experience reduced eosinophil-mediated lung inflammation in response to allergens and are less susceptible to obesity induced inflammation in response to a high fat diet." (PMID 28545453, 2017). "Thus, therapeutic strategies designed to modulate RORα activity may be beneficial for the treatment of hepatic disease as well as obesity-associated metabolic diseases." (PMID 28757615, 2017). "Together, our converging results propose RORA as an important intercellular effector in adipose tissue of aging and its interactions with obesity." (PMID 38297378, 2024). "Obesity resulted in overall disruption of core clock genes (i.e., Bmal1, Clock, Rev-erbα/Nr1d1, Rev-erbβ/Nr1d2, Per1, Per2, Cry1, Cry2, Dbp and Rorα) in WAT." (PMID 35198059, 2022). "Nevertheless, a HFD significantly increases body weight and the obesity phenotype in liver-specific Rorα conditional knockout mice (RORαLKO) compared with RORα-floxed mice (RORαf/f)." (PMID 34588606, 2021). "To investigate the role of macrophages RORα in metabolic functions, in particular obesity and IR, we fed WT and MKO mice with a 60% high fat diet (HFD) for 12 weeks." (PMID 33273527, 2020). "In the present work, we therefore generated a mouse line harboring RORα deletion in macrophages and evaluated its impact in models of obesity, IR and NASH." (PMID 33273527, 2020). "The staggerer mice (Rorasg/sg), which are carrying a natural mutation in the RORα LBD, are protected against diet-induced obesity, IR and NAFLD23,24." (PMID 33273527, 2020).
Obesity (continued). "Due to the pleiotropic effects and wide cell distribution of RORα and considering the key role of macrophages in metabolic diseases, we investigated the impact of RORα deletion in these cells on obesity, IR and NASH by using the LysM-Cre mice." (PMID 33273527, 2020). "Retinoic acid receptor-related orphan receptor-alpha (RORα) is a transcription factor from the nuclear receptor family expressed by immune cells and involved in the development of obesity, insulin resistance (IR) and non-alcoholic steatohepatitis (NASH)." (PMID 33273527, 2020). "Our study has shown a correlation between level of expression of RORα, inflammation, and resistance to diet- and age-induced obesity." (PMID 28744254, 2017). "Together, our data demonstrate that RORα controls PPARγ signaling to protect against hepatic metabolic homeostasis and obesity in response to HFD." (PMID 28757615, 2017). "Our data confirm that RORα is a key factor for the repression of PPARγ signaling to protect against diet-induced hepatic steatosis and obesity in vivo." (PMID 28757615, 2017). "To explore molecular mechanism by which hepatic deletion of RORα induces obesity and insulin resistance, we performed mRNA-sequencing analysis of liver tissues obtained from HFD-fed RORαf/f, HFD-fed RORαLKO, CD-fed RORαf/f and CD-fed RORαLKO mice." (PMID 28757615, 2017). "One focus of current research on obesity and diabetes is on the retinoid-related orphan receptor alpha (RORα) and its roles in glucose and lipid metabolism." (PMID 26812621, 2016). "The PubMed and Scopus databases were searched for studies reporting the association between circadian rhythm gene polymorphisms (ARNTL, BMAL1, CLOCK, CRY, PER, NPAS2, REV-ERBα, REV-ERBβ, and RORα) and MetS, and its comorbidities diabetes, obesity, and hypertension." (PMID 35053018, 2021). "A growing body of evidence also suggests a role for RORα in obesity, T2D and NAFLD." (PMID 33273527, 2020). "Improving our understanding of the interactions between RORα and its ligands may facilitate the development of specific drugs for the treatment of inflammation, metabolic diseases, obesity, and atherosclerosis." (PMID 32321446, 2020). "With this model, we will be able to better understand the role of RORα versus RORγ in these diseases and utilize this information to develop improved therapeutic strategies to manage and prevent obesity and related pathologies such as cardiovascular diseases and diabetes." (PMID 28744254, 2017). "High-fat diet (HFD)-fed liver-specific Rorα deficient mice (RORαLKO mice) show severe metabolic defects, including hepatic steatosis, obesity, and insulin resistance, although no physiological changes have been observed with control diet (CD)." (PMID 28757615, 2017). "In humans, two studies have revealed a connection between RORα, obesity, and type 2 diabetes." (PMID 23355833, 2013). "Because of their role in regulating various features of metabolic syndrome, RORα and γ antagonists might also have beneficial effects in the management of obesity and insulin resistance." (PMID 23355833, 2013). "Interestingly, it was recently reported that RORα-deficient mice, like S6K1-deficient mice, exhibit reduced fat-pad mass, smaller adipocytes, and resistance to diet-induced obesity." (PMID 20463884, 2010). "Finally, understanding the interaction between C/EBPβ and RORα may potentially help design specific drugs to treat inflammation, diabetes, and obesity." (PMID 26383638, 2015). "CRY2 expression was related to age, DBP expression was related to age, tumor type, smoking history, and RORA expression was related to TNM stage, obesity index, and tumor type in KIRP patients (p < 0.05)." (PMID 34977153, 2021). "Interestingly, RORα seems to be crucial for attenuated inflammatory response to maintain intestinal homeostasis, and therefore we can speculate that RORα activation could be involved in MaR1 beneficial actions on obesity-induced colon inflammation." (PMID 32751593, 2020).
Obesity (continued). "An intriguing observation in this study is that RORα is crucial to recruit HDAC3 to repress hepatic PPARγ-mediated lipogenic genes and protect against diet-induced hepatic steatosis and obesity." (PMID 28757615, 2017). "In both the obesity model and in response to LPS, there is reduced response to the inflammatory stimuli in the absence of RORα." (PMID 33767712, 2021). "Taken together, our results show that RORα deletion in macrophages has no impact on HFD-induced obesity and IR." (PMID 33273527, 2020). "Our results therefore show that RORα deletion in macrophages does not alter the development of obesity and IR and question its role in NASH." (PMID 33273527, 2020). "Yet, importantly, we found no impact of LysM-Cre-mediated RORα deletion neither on HFD-induced obesity, IR and steatosis nor on CDAA diet-induced NASH." (PMID 33273527, 2020). "In conclusion RORα deletion in macrophages using the LyzM-Cre system has no impact on the development of obesity, IR and NASH." (PMID 33273527, 2020). "RORA, a nuclear receptor superfamily member, links inflammatory and metabolic signaling, and its overexpression in VAT may contribute to dysfunction and insulin resistance in obesity." (PMID 41295281, 2025). "Altered DNA methylation in promoters of transcription factor genes (PPARA, KLF15, NR3C1, RORA and ATF4) known to regulate FGF21 expression and its binding receptors and co-factors (FGFR1, FGFR3 and FGFRL1 and KLB) has been revealed in relation to the elevated levels of circulating FGF21 in obesity." (PMID 33670024, 2021). "We report that RORα deletion in macrophages does not impact on HFD-induced obesity and IR." (PMID 33273527, 2020). "However, MTNR1A and RORA are not included in the main disease cluster studied, showing that MTNR1B, among melatonin receptors, has a stronger association to metabolic diseases such as obesity and diabetes." (PMID 40697662, 2025).
hepatocellular carcinoma (25 papers, 2012 to 2025). A malignant tumor that arises from hepatocytes. "In hepatocellular carcinoma, diminished RORA expression is associated with tumor growth, invasion, and poor prognosis." (PMID 40638694, 2025). "This suppression, linked to RORα-mediated decrease in pyruvate dehydrogenase kinase 2 expression, inhibits hepatoma growth through mechanisms involving the upregulation of p21, as observed in both in vitro and in vivo models." (PMID 39518891, 2024). "In the content of the liver, RORα is an essential regulator in bile acid and cholesterol homeostasis and mediates reprogramming of glucose metabolism in glutamine‐deficient hepatoma cells." (PMID 37051760, 2023). "Another role for RORα in cancer was revealed by a recent study demonstrating that RORα expression was decreased in tumor tissues compared to adjacent normal tissues in human hepatocellular carcinoma patients and that this was associated with a change in glucose metabolism." (PMID 26878025, 2015). "Investigating the expression of the CYP39A1 gene, it was described that the nuclear receptor RORα regulates CYP39A1 expression levels in human hepatoma cells." (PMID 39403150, 2024). "MiR-1246 was demonstrated to promote the progression of hepatocellular carcinoma through activating the RORα-Wnt/β-Catenin axis." (PMID 35959113, 2022). "RORα is also known to regulate multiple aspects of mitochondrial function and metabolism including glucose metabolism in hepatoma cells and lipid homeostasis in the liver and in macrophages." (PMID 34756888, 2021). "In human hepatoma cells, RORα was found to be upregulated after hypoxia induction, while RORα expression was lower in tumor tissues than in adjacent tumor tissues." (PMID 29904382, 2018). "Recent studies have shown that in hepatoma cells RORα reprograms glycolysis that is upregulated in gastric cancer for cell proliferation (Warburg effect)." (PMID 28052040, 2017). "A different study indicated a role for SPARC, which is critical in the regulation of cell growth and adhesion, in the anti-tumor and anti-proliferation effects of RORα in human hepatoma cells." (PMID 26878025, 2015). "Additionally, other studies have illustrated that the activation of RORα suppresses aerobic glycolysis and biosynthesis in hepatoma cells." (PMID 39518891, 2024). "In addition, RORα inhibited hepatocellular carcinoma proliferation, invasion and migration through downregulation of chemokine CXCL5." (PMID 38184549, 2024). "Interestingly, hypoxia increases RORα transcription in a hepatoma cell line by binding to a hypoxia response element in the RORα promoter, indicating the potential for reciprocal regulation of RORα and HIF-1α." (PMID 34756888, 2021). "Moreover, the RBP SORBS2 restricts hepatocellular carcinoma tumourigenesis and metastasis through enhancing RORA mRNA stability." (PMID 34861864, 2021). "However, the association of melatonergic genes with one specific cancer type, hepatocellular carcinoma, identified RORA as a tumor suppressor and a prognostic marker for patients with hepatocellular carcinoma." (PMID 33842355, 2021). "siRNA-mediated knockdown of RORα significantly downregulated NCEH1 expression and accumulated lipid droplets in human hepatoma cells." (PMID 32321446, 2020). "CYP39A1 was upregulated by RORα overexpression in HEK293 cells, while RORα knockdown by siRNA significantly downregulated CYP39A1 expression in human hepatoma cells." (PMID 32392803, 2020). "We showed, for the first time, that the nuclear receptor RORα regulates CYP39A1 expression levels in human hepatoma cells, which can be induced by SR1078, a RORα agonist." (PMID 32392803, 2020).
hepatocellular carcinoma (continued). "RORA could act as a repressor in LUAD and the finding was consistent with previous studies on cancers, such as prostate cancer and hepatocellular carcinoma." (PMID 35504868, 2022). "Moreover, CYP39A1 was upregulated through RORα overexpression in HEK293 cells, while RORα knockdown by siRNA significantly downregulated CYP39A1 expression in human hepatoma cells, suggesting that CYP39A1 expression is activated via RORα nuclear receptors." (PMID 32392803, 2020). "Moreover, reduced RORα levels correlated with shorter OST in patients with breast and hepatocellular cancers." (PMID 27542227, 2016). "Overexpression of RORα or treatment with SR1078, the RORα activator, reduced aerobic glycolysis, down-regulated biosynthetic pathways, reduced PDK2 expression, inhibited the phosphorylation of pyruvate dehydrogenase, and subsequently shifted pyruvate to complete oxidation in hepatoma cells." (PMID 33739396, 2021). "Our results suggest that RORα activators could provide a good strategy for the development of effective therapeutics for liver diseases mediated by the IL-6Rα–STAT3 axis, such as hepatic injury with APR and hepatocellular carcinoma." (PMID 31409825, 2019).